CHRAC1 (chromatin accessibility complex subunit 1)
Description:
Forms a complex with DNA polymerase epsilon subunit POLE3 and binds naked DNA, which is then incorporated into chromatin, aided by the nucleosome remodeling activity of ISWI/SNF2H and ACF1. Does not enhance nucleosome sliding activity of the ACF-5 ISWI chromatin remodeling complex.
Synonyms: CHRAC-1; CHRAC-15; CHRAC15; YCL1; CHARC1; CHARC15
Tractability: PROTAC: ubiquitination databases record sites on it; its protein half-life has been measured.
Gene: Protein-coding gene on chromosome 8 (140,511,311 to 140,517,154, forward strand). Ensembl gene ENSG00000104472.
Subcellular location: Nucleus
Subcellular location (Human Protein Atlas): Nucleoplasm
Gene Ontology:
Molecular function: protein binding; DNA binding; DNA-directed DNA polymerase activity; protein heterodimerization activity
Biological process: chromatin remodeling; nucleosome assembly; regulation of DNA replication; DNA-templated DNA replication; DNA biosynthetic process
Cellular component: CHRAC; epsilon DNA polymerase complex; nucleus; pericentric heterochromatin
Genetic constraint (gnomAD): Loss-of-function variants: 4 observed, 5.18 expected, observed/expected ratio (o/e) 0.77, 90% interval 0.38 to 1.65. That is too few expected variants to judge how well the gene tolerates losing a copy. Missense variants: 134 observed, 96.57 expected, observed/expected ratio (o/e) 1.39, 90% interval 1.21 to 1.6. Synonymous variants: 67 observed, 42.03 expected, observed/expected ratio (o/e) 1.59, 90% interval 1.3 to 1.9.
Homologues: Orthologues: chimpanzee CHRAC1 (99% identical), macaque CHRAC1 (98% identical), guinea pig CHRAC1 (85% identical), dog CHRAC1 (83% identical), pig CHRAC1 (82% identical), mouse Chrac1 (79% identical), tropical clawed frog chrac1 (66% identical).
Diseases named in the same sentence as CHRAC1 in open-access papers:
CHRAC1 is named in the same sentence as 8 diseases in open-access papers, as found by Europe PMC text mining. Sharing a sentence is not in itself a finding about the gene and the disease. The quoted sentences say what the papers report.
ovarian carcinoma (4 papers, 2022 to 2025). A malignant neoplasm originating from the surface ovarian epithelium. "Taken together, lncRNA PART1 targeted miR-512-3p/CHRAC1 axis to increase cisplatin resistance in ovarian cancer." (PMID 36105363, 2022). "PART1 can target miR-512-3p and regulate the expression of CHRAC1 in ovarian cancer cells." (PMID 36105363, 2022). "In addition, CHRAC1 expression level was increased in cisplatin resistant ovarian cancer cell lines and lung cancer tumor tissues, and CHRAC1 disruption inhibited the migration and invasion of cisplatin resistant ovarian cancer cells and H1299 lung cancer cells." (PMID 38223760, 2024). "In ovarian cancer, YY1 induces the transcription of PART1, enhances resistance to cisplatin, and inhibits apoptosis by modulating the miR-512-3p/chromatin accessibility complex subunit 1 (CHRAC1) axis." (PMID 40867514, 2025).
breast carcinoma (3 papers, 2016 to 2025). "As for CHRAC complexes, the CHRAC1 gene is amplified on chromosome 8q24.3 and it is confirmed to be a driver gene that promotes the proliferation and clonal survival of breast cancer cells." (PMID 41278204, 2025). "CHRAC1 was elevated in cervical and breast cancer biopsies and the upregulation correlated with shorter survival, poor pathological stages and metastasis of cancer patients." (PMID 38223760, 2024). "However, CHRAC1 is known to potentially interact with YAP in breast cancer and exerts its tumorigenesis effect by enhancing YAP target oncogenes, which are involved in the Hippo pathway." (PMID 41278204, 2025). "Moreover, in breast cancer specimens (n = 48), CHRAC1 expression increased with the progression of tumor stage." (PMID 38223760, 2024). "Also, a recent study showed suggestive associations between DAE associated variants located in breast cancer susceptibility chromosomal regions, and prognosis (ZNF331 and CHRAC1)." (PMID 27792995, 2016). "The components of ACF and CHRAC complexes, including BAZ1A, CHRAC1, and POLE3, are also upregulated in breast cancers." (PMID 41278204, 2025). "Despite its significant alteration rate and role as a driver gene for breast cancers, CHRAC1 does not possess a bromodomain and presents a significant challenge in developing small-molecule inhibitors." (PMID 41278204, 2025). "Hence, targeting the interaction between CHRAC1 and YAP can provide an essential and novel approach to breast cancer treatment strategy." (PMID 41278204, 2025).
cervical cancer (2 papers, 2022 to 2024). A primary or metastatic malignant neoplasm involving the cervix. "To validate the effect of CHRAC1 on cancer progression, we silenced CHRAC1 in breast and cervical cancer cell lines (MDA-MB-231 and Hela)." (PMID 38223760, 2024). "Collectively, these data suggest that CHRAC1 silencing inhibits the proliferation of breast and cervical cancer cells." (PMID 38223760, 2024). "To further investigate the clinical significance of CHRAC1, we conducted IHC analysis in human breast and cervical cancer biopsies." (PMID 38223760, 2024). "Collectively, these data display that CHRAC1 silencing suppresses tumor growth of breast and cervical cancer cells in nude mice." (PMID 38223760, 2024). "In cervical cancer specimens (n = 48), patients with metastasis had elevated CHRAC1 protein expression compared to those patients with primary tumors." (PMID 38223760, 2024). "In in vitro study, we discovered that knockdown of CHRAC1 restrained the growth of breast and cervical cancer cells." (PMID 38223760, 2024). "This research aimed to determine the function of CHRAC1 in breast and cervical cancer and elucidate the molecular mechanism." (PMID 38223760, 2024). "Immunohistochemistry (IHC) result displayed that CHRAC1 was mainly expressed in the nucleus and the staining was extremely weak in para-tumor tissues, while breast and cervical cancer biopsies showed strong CHRAC1 signal." (PMID 38223760, 2024). "Thus, CHRAC1 is elevated in breast and cervical cancer and the upregulation correlates well with YAP." (PMID 38223760, 2024). "Together, these data manifest that high CHRAC1 expression may predict advanced pathological tumor stages and poor survival in breast and cervical cancer." (PMID 38223760, 2024). "In addition, both breast and cervical cancer biopsies with high CHRAC1 expression showed stronger YAP staining." (PMID 38223760, 2024). "Moreover, YAP was also highly expressed in breast and cervical cancer specimens with high expression of CHRAC1." (PMID 38223760, 2024). "CHRAC1 depletion suppressed breast and cervical cancer cell proliferation and tumor growth." (PMID 38223760, 2024). "Moreover, CHRAC1 expression was statistically associated with YAP in breast and cervical cancer biopsies." (PMID 38223760, 2024). "In the current research, we identified CHRAC1 as a potential YAP interactor using the Bio-ID method and demonstrated that CHRAC1 regulated cell proliferation through promoting the oncogenic transcription of YAP target oncogenes in breast and cervical cancer." (PMID 38223760, 2024).
endometriosis (1 paper, 2022). The growth of functional endometrial tissue in anatomic sites outside the uterine body. "Most notably, ARID1A in endometriosis-related OC, SMARCA4, and SMARCB1 in hypercalcemic type small cell ovarian carcinoma (SCCOHT), ACTL6A, CHRAC1, RSF1 amplification in high-grade serous OC." (PMID 36430148, 2022).
cancer (2 papers, 2020 to 2024). A tumor composed of atypical neoplastic, often pleomorphic cells that invade other tissues. "Despite this, specimens from different cancer types are required to verify the association between CHRAC1 and YAP." (PMID 38223760, 2024). "CHRAC1, a component of the chromatin remodeling complex, is associated with poor prognosis of cancer patients." (PMID 38223760, 2024). "Moreover, CHRAC1 is frequently upregulated in diverse cancers and the upregulation is statistically associated with YAP activation and poor prognosis in cancer patients." (PMID 38223760, 2024). "In addition, researches have reported that abnormal expression of CHRAC1 is frequently associated with the occurrence and progression of human cancer." (PMID 38223760, 2024). "In this study, we identified CHRAC1 as a potential oncogene in multiple human tumors via pan-cancer analyses and experimental verification." (PMID 38223760, 2024). "To explore the expression of CHRAC1 in cancer tissues, we analyzed the expression of CHRAC1 in cancer tissues including breast and cervical." (PMID 38223760, 2024). "In summary, our study found that depletion of CHRAC1 suppresses cancer cell proliferation and tumor growth." (PMID 38223760, 2024). "CCK8, colony formation and subcutaneous xenograft assays were conducted to explore the function of CHRAC1 in cancer cell proliferation." (PMID 38223760, 2024). "First of all, we discovered that CHRAC1 was upregulated in a variety of cancer tissues compared to relevant normal tissues." (PMID 38223760, 2024). "Consistent with this, there was significant correlation ( p < 0.0001) between YAP and CHRAC1 in these cancer biopsies." (PMID 38223760, 2024). "The expression of CHRAC1 in cancer tissues was significantly higher than that in the para-cancer group." (PMID 38223760, 2024). "Then, we investigated the clinical correlation of CHRAC1 and YAP and found CHRAC1 was associated with YAP across Pan-cancer, including BRCA and CESC in TCGA database." (PMID 38223760, 2024). "To make the knockdown data more compelling, we also investigated the effect of CHRAC1 over-expression on cancer cells." (PMID 38223760, 2024). "To clarify how CHRAC1 affects cancer development, we conducted RNA-seq assay and found that the transcription program of control cells and CHRAC1 knockdown cells was significantly different." (PMID 38223760, 2024). "The inhibition of CHRAC1 also affected the expression level of many cancer hallmarks." (PMID 38223760, 2024). "Wound-healing assay also indicated that CHRAC1 down-regulation restrained cancer cell migration." (PMID 38223760, 2024). "Collectively, these findings indicate that elevated CHRAC1 may be a prognostic factor for cancer." (PMID 38223760, 2024). "Together, our findings reveal that CHRAC1 plays a crucial role in enhancing YAP transcription activity and tumorigenesis, suggesting it may be a potential target for cancer therapy." (PMID 38223760, 2024). "Although previous studies have reported the significance of CHRAC1 in the progression of several cancers, the mechanism has not been well studied and the role of CHRAC1 in other cancers remains to be elucidated." (PMID 38223760, 2024). "However, the mechanism remains to be clarified and the function of CHRAC1 in various cancer types has not been fully studied." (PMID 38223760, 2024). "However, the significance of CHRAC1 in cancer progression has not been investigated extensively." (PMID 38223760, 2024). "However, the significance of CHRAC1 in cancer development has not been investigated extensively." (PMID 38223760, 2024).
tumor (2 papers, 2010 to 2024). "Meanwhile, CHRAC1 expression was statistically correlated with poor survival and pathological stages in various tumor types." (PMID 38223760, 2024). "In in vivo study, we demonstrated that CHRAC1 silencing decreased tumor weight and tumor size in MDA-MB-231 and Hela xenograft mouse model." (PMID 38223760, 2024). "The potential mechanism may be that CHRAC1 interacts with YAP to enhance the transcription of YAP down-stream oncogenes to promote tumor growth." (PMID 38223760, 2024). "These indicate that CHRAC1 may promote tumor growth by enhancing the oncogenic transcription of YAP." (PMID 38223760, 2024). "High CHRAC1 mRNA level was correlated with decreased overall and disease-free survival in cases of CESC and other tumor types by using the Gene Expression Profiling Interactive Analysis version 2 (GEPIA2) tool." (PMID 38223760, 2024). "However, whether CHRAC1 affects tumor metastasis needs further study." (PMID 38223760, 2024). "Downregulation of CHRAC1 in Hela cells could significantly reduce tumor size, and tumor formation was not possible in MDA-MB-231 cells with CHRAC1 inhibition." (PMID 38223760, 2024).
CHRAC1 also shares sentences with these, for which no sentence is quoted: gynecological tumor (1 paper); lung carcinoma (1).